TLR9 (toll like receptor 9)
Diseases named in the same sentence as TLR9 in open-access papers (continued):
Sharing a sentence is not in itself a finding about the gene and the disease.
systemic inflammatory response syndrome (12 papers, 2016 to 2023). SIRS is a serious condition related to systemic inflammation, organ dysfunction, and organ failure. "Mitochondrial DNA can activate polymorphonuclear neutrophils through CpG/TLR9 interactions in sterile systemic inflammatory response syndrome (SIRS) associated with acute trauma." (PMID 26498951, 2016). "It was suggested that SAT05f can recruit surface TLR9+ (sTLR9) neutrophils to play a protective role in the development of systemic inflammatory response syndrome (SIRS) in locally inflammatory areas." (PMID 36825156, 2023). "Mitochondrial DNA is a DAMP that upregulates the innate immune responses through TLR-9 activation during sterile systemic inflammatory response syndrome and leads to the release of proinflammatory cytokines." (PMID 36864213, 2023). "And, mtDNA contributes to the initiation of sterile systemic inflammatory response syndrome (SIRS) via activating the TLR9/NF-kB pathway and inducing pro-inflammatory cytokines expression." (PMID 33239048, 2020). "Mitochondrial DNA (mtDNA) of RTCEs, which is released from damaged and/or dead cells, could be identified as a “danger” signal and is able to activate the TLR9 pathway, contributing to the activation of neutrophils and the initiation of systemic inflammatory response syndrome (SIRS)." (PMID 36010680, 2022). "Intervention with mtDNA in an animal study induced systemic inflammatory response syndrome (SIRS) and pulmonary edema, and blockade of TLR9 improved the lung histopathological changes, wet/dry ratios and inflammatory factor concentrations." (PMID 33632166, 2021). "Cell surface TLR9 is recently reported in neutrophils in systemic inflammatory response syndrome (SIRS) where it is believed to play a protective role against aggressive SIRS, although whether histones would play any role in surface TLR9 activation in such a case is not known." (PMID 30577532, 2018). "Interestingly, TLR9 has also been found to recognize mtDNA released into the bloodstream during systemic inflammatory response syndrome (SIRS) and activate a p38-mediated inflammatory response." (PMID 37325622, 2023).
ulcerative colitis (12 papers, 2012 to 2025). An inflammatory bowel disease involving the mucosal surface of the large intestine and rectum. "Recently, a study has shown induction of IL‐10 producing Tregs and wound healing macrophages in mouse models of ulcerative colitis in a TLR9‐dependent manner." (PMID 37406035, 2022). "It has also been demonstrated that among others, TLR9 expression increases in active ulcerative colitis patients, and that the mRNA levels positively correlate with the severity of intestinal inflammation as well as with inflammatory cytokines." (PMID 29883450, 2018). "We determined the safety and efficacy of the TLR-9 agonist DNA-based immunomodulatory sequence 0150 [DIMS0150] in ulcerative colitis [UC] patients refractory to standard therapy." (PMID 27208386, 2016). "This protective role of TLR9 is demonstrated by positive outcomes from experimental treatments using synthetic CpG-based TLR9 agonists on adults and mice with ulcerative colitis, reducing symptoms by targeting the imbalance between mucosal TLR9 and TLR4 activation." (PMID 39770994, 2024). "Unlike many of the TLRs, TLR9 modulation has been studied clinically in patients with ulcerative colitis using a TLR9 agonist, DIMS0150 (also known as cobitolimod/Kappaproct)." (PMID 29515999, 2018).
Hepatic steatosis (11 papers, 2015 to 2025). Steatosis is a term used to denote lipid accumulation within hepatocytes. "Mice deficient in TLR9 have been documented to be protected from HFD-induced liver steatosis and inflammation, thus pointing out the importance of the TLR-9 pathway in modulating inflammation in NASH." (PMID 35053205, 2021). "TLR9 deficiency also exhibited enhanced hepatic steatosis after high fat diet feeding in mice." (PMID 34262465, 2021). "The pathogenetic role of microbe-derived metabolites is well established in animal model studies, showing that hepatic steatosis, inflammation and fibrosis are attenuated in TLR-4- and TLR-9-deficient mice on a high-fat or choline-deficient diet." (PMID 36986052, 2023). "A recent study of NASH showed that the production of IL-1β by Kupffer cells induced by TLR9 signaling results in hepatic steatosis, inflammation, and fibrosis." (PMID 28493939, 2017). "Different animal models reveal that inflammasome deficiency-associated changes in the gut microbiota composition were associated with exacerbated hepatic steatosis and inflammation through the influx of TLR4 and TLR9 agonists into the portal circulation." (PMID 26090468, 2015). "Moreover, in a mice model of hepatic steatosis, changes in gut microbiota are associated with exacerbated hepatic steatosis and inflammation through portal influx of TLR4 and TLR9 agonists, leading to enhanced hepatic tumor-necrosis factor (TNF)-α expression that drives NASH progression." (PMID 36986052, 2023). "Activation of the TLR4 by LPS or TLR-9 by DNA derived from intestinal bacteria promotes steatohepatitis, while suppression of the TLR4 or TLR-9 attenuates liver steatosis, inflammation, and fibrosis in a few of mouse models of NASH." (PMID 36032141, 2022). "This occurs by means of the portal inflow of TLR-4 and TLR-9 agonists in mice, leading to heightened hepatic tumor necrosis factor alpha (TNF-α) expression and inflammation, a phenomenon particularly pronounced in mouse models of hepatic steatosis." (PMID 38613058, 2024). "Furthermore, TLR9 deficiency significantly reduced liver weights and ameliorated hepatic steatosis in HFD-induced NASH mice, indicating the protective role of TLR9 in hepatic dysmetabolism." (PMID 37020586, 2023). "Similar with TLR4, the mRNA level of TLR9 was significantly upregulated in patients with NASH, but not in patients with hepatic steatosis." (PMID 37020586, 2023).
ischemia (11 papers, 2014 to 2023). A hypoperfusion of the BLOOD through an organ or tissue caused by a PATHOLOGIC CONSTRICTION or obstruction of its BLOOD VESSELS, or an absence of BLOOD CIRCULATION. "We found that TLR9 deficiency reduced the accumulation of granulocytes in the kidney in case of severe ischemia." (PMID 26361210, 2015). "These oligomers work to ameliorate myocardial inflammation by acting as agonistic ligands for toll-like receptor 9 (TLR-9), immune receptors responsible for detecting damage associated molecular patterns (DAMPs) which are released during ischemia related cell damage." (PMID 38993918, 2023). "It has also been reported in a hepatic ischemia/reperfusion injury model that blocking TLR9 can downregulate the expression of PAD4 and Rac2, which are essential for NETs formation." (PMID 37365190, 2023). "Taken together, these results demonstrated that the TLR9 – IFN-I pathway inside myocardium was activated during ischemia and mediated ischemic myocardial infarction." (PMID 36081846, 2022). "HMGB1 and cfDNA released from ischemic myocardium activated the intra-myocardial TLR9 – IFN-I inflammatory pathway during ischemia and the extra-myocardial TLR9 – IFN-I inflammatory pathway during reperfusion." (PMID 36081846, 2022). "HMGB1 and cfDNA released from ischemic myocardium activated the intra-myocardial TLR9 – IFN-I inflammatory pathway during ischemia and extra-myocardial TLR9 – IFN-I inflammatory pathway during reperfusion." (PMID 36081846, 2022). "This study investigated the role of TLR9 in blood flow recovery in the ischemic limb using a mouse hind-limb ischemia model." (PMID 30460242, 2018). "In a mice model of the hepatic ischemia/reperfusion injury, the extracellular histones released from liver parenchymal cells have been shown to exacerbate liver injuries through Toll-like receptor-9 activation." (PMID 28060824, 2017). "In conclusion, systemic TLR9-activation upon onset of ischemia results in definite alterations in cardiac, as well as systemic, inflammatory responses, but does not impact infarct extension." (PMID 25126943, 2014). "Since HCQ inhibits the TLR9 – IFN-I pathway, we further hypothesize that administration of HCQ will attenuate the inflammatory response and associated post-ischemia reperfusion injury." (PMID 36081846, 2022). "Similarly, the extracellular histone–TLR9–MyD88 pathway has been also reported in a hepatic ischemia/reperfusion injury model, as shown by the inhibitory effect of an anti-histone antibody and as observed in TLR9- and MyD88-knockout mice." (PMID 27656184, 2016). "Therefore, we exposed wild-type and TLR9KO mice to moderate (20 minutes) or severe (30 minutes) ischemia and sacrificed mice at one day of reperfusion to investigate the pathological processes preceding TLR9-mediated death." (PMID 26361210, 2015). "Thus, even though we cannot exclude cardiac influences during ischemia, our experimental set-up suggests a predominant effect of TLR9-stimulation during reperfusion." (PMID 25126943, 2014). "Thus, in the current study we investigated the pathophysiological consequence of intervening with the TLR9-agonist CpG B during onset of ischemia." (PMID 25126943, 2014). "Systemic TLR9-stimulation upon onset of ischemia and subsequent reperfusion does not alter final infarct size despite causing clear alterations of both systemic and cardiac inflammatory parameters." (PMID 25126943, 2014). "Activation of the innate immune receptor toll-like receptors (TLR) 9 prior to ischemia and reperfusion (I/R) reduces infarct size, but the consequence of TLR9 activation timed to the onset of ischemia is not known." (PMID 25126943, 2014).
multiple sclerosis (11 papers, 2011 to 2026). A progressive autoimmune disorder affecting the central nervous system resulting in demyelination. "Recently, it has been demonstrated that MIS416, a novel immunomodulatory microparticle that activates NOD-2 and TLR-9-signaling, has disease-modifying activity in multiple sclerosis models." (PMID 29321652, 2018). "In vivo treatment with IFN-β induces TLR7 upregulation and TLR9 down modulation in PBMCs of patients with multiple sclerosis." (PMID 29052537, 2017). "In the setting of neurological disease, the described abnormalities also appear to be specific, since with multiple sclerosis, the TLR-9 pathway was impaired." (PMID 23951210, 2013). "TLR9 can have a more regulatory function or enhance pathologic processes in the same animal model of multiple sclerosis." (PMID 23016675, 2012). "Activated via TLR-9, pDCs also secrete large amounts of type I interferon which are involved either in stimulation or down regulation of immune response in multiple sclerosis (MS)." (PMID 21214939, 2011). "Additionally, in an experimental autoimmune encephalomyelitis (EAE) animal model of multiple sclerosis, pathogens have been attributed to TLR9-mediated innate immunity." (PMID 37264476, 2023). "Using a mouse model of multiple sclerosis, we are investigating the pathways by which activation of TLR9 and NOD2 may modify the innate immune environment and the subsequent T cell-mediated autoimmune responses." (PMID 24498172, 2014).
myeloma (11 papers, 2013 to 2024). "Their preventive role against early cancer development has been reported in mouse models of myeloma and mesothelioma after infection and was confirmed here after TLR9 ligation." (PMID 36714124, 2022). "More recent study from this group has identified a novel TLR-9 agonist that inhibited pDC-induced myeloma cell growth and triggered apoptosis, restoring the T cell stimulation." (PMID 34442012, 2021). "Co‐expression of TLR1, TLR7 and TLR9 in myeloma cells has shown to be involved in induction of drug resistance." (PMID 33336901, 2021). "Using RPMI 8226, a human myeloma B cell line, it was shown that HBsAg induced TLR9 dysfunction by suppressing HBsAg-induced phosphorylation, which activated the transcription factor, CREB, thereby preventing TLR9 promoter activity." (PMID 34638802, 2021). "Analysis of toll-like receptor (TLR) expression at protein level indicated that TLR1, TLR3, TLR4, TLR7, TLR8, and TLR9, were similarly expressed in most human myeloma cell lines, including L363 and RPMI 8226 cells, as well as in primary cells from MM patients." (PMID 28702457, 2017). "Expression of mRNA for TLR1, TLR3, TLR4, TLR5, TLR7, TLR8, and TLR9 was found in all myeloma cell, but levels of mRNA expression differed amongst different cell lines." (PMID 23593278, 2013). "This concept has been explored to enhance immune responses in hematopoietic cancers, whereby targeting STAT3 specifically in TLR9 expressing cancer cells can be achieved using CpG based delivery of silencing oligos results in growth inhibition of myeloma and myeloid leukemia." (PMID 24722453, 2014). "We show here that TLR4 and TLR9 signaling downregulated BCMA in MM cells at both the gene and protein levels and that approximately 50% of patients’ myeloma cells also respond to TLR activation by downregulating BCMA." (PMID 38911853, 2024).
non-small cell lung carcinoma (11 papers, 2005 to 2024). A group of at least three distinct histological types of lung cancer, including non-small cell squamous cell carcinoma, adenocarcinoma, and large cell carcinoma. "In fact, preclinical studies on TLR9 agonists demonstrate that these increase antigen-specific T cells in multiple tumour types, including breast cancer, colorectal and non-small-cell lung carcinoma (NSCLC)." (PMID 36551788, 2022). "To study the prophylactic efficacy of the TLR9 agonist CpG-C in reducing brain metastasis, we first employed two models of non-small-cell lung carcinoma, given the clinical prevalence of brain metastases in this type of cancer." (PMID 30921319, 2019). "By application of a novel fixation technique we specify for the first time the expression of TLR9 protein and mRNA in a selection of human non small cell lung cancer tissues as well as cell lines." (PMID 15631627, 2005). "Failure of a different TLR9 agonist to improve outcomes in advanced non-small cell lung cancer when added to chemotherapy suggests that the supportive immune response initiated by TLR9 agonists may firstly require release of tumour-associated antigens." (PMID 24816725, 2014). "NK cell recruitment in non-small-cell lung cancer (NSCLC) model was also obtained by using litenimod (Li28), a TLR9 agonist, in combination with the immunotherapeutic vaccine based on modified vaccinia virus Ankara (MVA), namely TG4010." (PMID 36672572, 2022). "It has been demonstrated that in non-small-cell lung cancer (NSCLC) cells, radiotherapy combined with TLR9 stimulation by the CpG ODN 7909 was able to downregulate PD-L1 (programmed death-ligand 1) expression which plays an important role in tumor immune escapes." (PMID 31886298, 2019).
ovarian carcinoma (11 papers, 2012 to 2025). A malignant neoplasm originating from the surface ovarian epithelium. "In addition, it has also been demonstrated that TLR9 expression is associated with poor differentiation in ovarian cancer specimens, and that its overexpression and stimulation enhances the migratory capacity of ovarian cancer cells." (PMID 22530148, 2012). "In an ovarian cancer model, the combination of TLR9 agonists (CpG oligodeoxynucleotides, CpG-ODNs) and anti-PD-1 antibodies can influence macrophage polarization by shifting them toward an immunoregulatory phenotype." (PMID 40330466, 2025). "We evaluated the contribution of macrophages to the effect of combinatorial immunotherapeutic treatments based on TLR9 stimulation (with CpG-ODNs) and PD-1 blockade in an ovarian cancer preclinical model." (PMID 34439233, 2021). "The administration of CpG oligodeoxynucleotides (CpG-ODN) could be a promising method to control ovarian cancers by targeting Toll-like receptor 9 (TLR9) and activating the immune system." (PMID 35631583, 2022). "Moreover, TLR9 was expressed both on the membrane and in the cytoplasm of epithelial cells from the ovarian cancer cell line SKOV3." (PMID 36231099, 2022). "However, the expression level of TLR9 in ovarian cancer cell lines was significantly lower than that in the normal." (PMID 32329191, 2020). "Although differences in the distribution of TLR9 in mice and humans and the enrichment of this receptor on innate immune cells of athymic mice must be considered, our results indicate a promising strategy to treat ovarian cancer patients with bulky ascites." (PMID 23360557, 2013). "Thus, the combination of TLR9 stimulation and PD-1 blockade reshapes macrophages into a more suppressive, tumor-promoting state, limiting the potential therapeutic benefit of this regimen in ovarian cancer." (PMID 40330466, 2025). "It is suggested that the expression of TLRs, TLR4, TLR9 and TLR10 was significantly reduced in the local macrophage‐infiltrating microenvironment of ovarian cancers." (PMID 32329191, 2020). "The expression levels of TLR4, TLR9 and TLR10 were significantly enhanced in the local macrophage‐infiltrating microenvironment of ovarian cancer." (PMID 32329191, 2020). "Myeloid cell depletion is able to enhance vaccine efficacy since immunization with TLR9 and NOD-2 containing microparticles followed by anti-CD11 treatment further delayed tumor progression in a mouse model of epithelial ovarian cancer." (PMID 27886105, 2016).